IL22 (interleukin 22)
Diseases named in the same sentence as IL22 in open-access papers (continued):
Sharing a sentence is not in itself a finding about the gene and the disease.
colitis (continued). "Still, no research on Bacteroides, indole synthesis, and IL-22 secretion has been conducted, so further studies are needed to verify the possibility that IAA produced by other Bacteroides activates IL-22 and reduces colitis." (PMID 35784338, 2022). "Taken together, these results demonstrated that colitis in TAM-treated Klf5ΔIND mice exhibited a strong Th17 phenotype that was associated with significant increases in IL-17A and IL-22 levels." (PMID 35393949, 2022). "Altogether, this data suggest that humanization of TNFR2 signaling is dispensable for the recovery from colitis, regulation of IL-22/IL-22 BP expression and recruitment of myeloid cells." (PMID 35383266, 2022). "Our study revealed that the secretion level of IL-22 was increased in the serum of rCsCP and CsCA-treated colitis mice, whereas the transcription level in the colon was decreased." (PMID 36084127, 2022). "In our study, IL-6 levels were higher in patients with thyroiditis and colitis, while IL-22 and SCF levels were higher in patients with colitis." (PMID 36159840, 2022). "The Trp metabolite Iald can activate aromatic hydrocarbon receptor (AHR) and induce the expression of interleukin-22 (IL-22) to improve the intestinal barrier and alleviate colitis in mice." (PMID 36238574, 2022). "During chronic inflammation, IL-22 is induced and often protects against damaging tissues similar to IL-10, specifically exerting its effects during acute inflammation in mouse colitis models." (PMID 36142515, 2022). "In this study, we probe the clinical and functional significance of the IL-22 responsive transcriptional program in diseased tissue of UC patients treated with ustekinumab and in multiple models of colitis." (PMID 36192482, 2022). "We aimed to verify the treatment effect of bioactive compounds including IL-22 and lncRNAs in UC on colitis mice." (PMID 36092152, 2022). "IL-22 is considered to play a protective role when acute colitis occurs; however, it is also found that IL-22 cooperates with IL17A to mediate pathogenicity in chronic colitis." (PMID 35273921, 2022). "Retinoic acid, an important mediator of T cell recruitment to the intestinal mucosa, is deficient in colitis-associated CRC and also enhances IL-22 secretion from γδ T cells, which suppresses intestinal inflammation." (PMID 35316367, 2022). "Vitamin C insufficiency resulted in decreased IL-22 and mucin production and increased the production of IL-6 in the DSS-induced colons of vitamin C-insufficient KO mice, which seems to cause severe colitis." (PMID 36142515, 2022). "As previously discussed (under DSS colitis), IL-23 synergises with IL-17, IL-21, and IL-22 to drive colon inflammation in the event of defective immune regulation mechanisms." (PMID 36012618, 2022). "During colitis in mice, expression of IL-22 was negatively impacted by accumulating Tregs which suppressed the release of IL-23 and IL-1b from macrophages." (PMID 36189323, 2022). "This was further confirmed by a colitis model in which transferred IL-22+T cells gained IFN-γ and IL-17 productions." (PMID 35911703, 2022). "These functions of ginger derived EV RNAs can ameliorate mouse colitis via IL-22-dependent mechanisms." (PMID 35745626, 2022). "Despite the increase in IL-22+-ILC3s under the colitis condition, the cell number remained comparable between the DSS and DSS+DKT groups." (PMID 35720414, 2022). "Since TNF blockade affected not only colonic IL-22BP expression, but also its serum levels in the humanized mouse, TNF-dependent colitis model, we next quantified human IL22-BP in IBD patients." (PMID 35383266, 2022). "The stimulation of triggering receptor expressed on myeloid cell (TREM)−1 with an agonistic antibody induced CD177 + neutrophils that produced NETs and IL22 and induced pathogen clearance and wound healing, alleviating colitis." (PMID 35039631, 2022). "GSVA demonstrated significant enrichment of the mouse IL-22 responsive transcriptional module across 6 different colitis models." (PMID 36192482, 2022).
colitis (continued). "Using in vivo models, IL-22 has been shown to be protective against pathogen-induced colitis, including C. rodentium and Salmonella typhimurium, and facilitates the clearance of pathogenic fungi." (PMID 36142193, 2022). "The observed upregulation of Reg3g and Fut2 by DKT in the colonic epithelial cells prompted us to interrogate the involvement of IL-22 in DKT-mediated amelioration of colitis." (PMID 35720414, 2022). "Data presented so far revealed that T cell-derived TNF controls IL-22 mediated epithelial restitution during colitis in the humanized TNF mouse model." (PMID 35383266, 2022). "On this basis, we focused the experiment on the protective role of IL-22 from NKp46+ cells regulated by vitamin C on DSS-induced colitis." (PMID 36142515, 2022). "The IL-22-regulated transcriptome was highly conserved between man and mouse and was highly enriched in the colon of both human and mouse colitis." (PMID 36192482, 2022). "We also observed that DSS‐induced colitis in Il34−/− rats led to increased levels of pro‐inflammatory cytokines Il6, Il1b, Il22 and a trend for an increase for Il17a, all involved in gut inflammation, whereas Ifng was decreased." (PMID 36030499, 2022). "Studies on a mouse model of colitis support the relevance of colonic epithelial ER stress in the development of chronic colitis and implicate the interleukin-23/interleukin-22-axis as a driver of the ER stress response." (PMID 35805947, 2022). "In a previous study using a DSS-induced colitis mouse model, the authors noted attenuation of colitis through gene transfer of Gstt1 via an IL-22-dependent pathway." (PMID 35743732, 2022). "ILC3 express the RA receptor and RA stimulates IL-22 production during homeostasis as well as during colitis in mice." (PMID 36189323, 2022). "Studies using mouse colitis models that recapitulate different aspects of human IBD have shown that IL-22 biology is important in colitis severity." (PMID 34868019, 2021). "Taken together, these findings suggest that IL22-producing ILC3s suppress DSS-induced acute colitis in Yeti mice." (PMID 33513946, 2021). "In the intestine, it has been described that IL-36 cytokines induce and amplify the expression of the IL-23/IL-22 axis, as IL-36R-/- mice with DSS-induced colitis present with reduced expression of IL-23 and IL-22 in the intestine compared to WT mice." (PMID 34887860, 2021). "The role of IL-22 in colitis is still controversial: while IL-22 has a protective effect on gut epithelium in acute injuries, it also enhances colitis in a context-dependent manner." (PMID 34992594, 2021). "A recent study found that I3C reduces colitis by preventing microbial dysbiosis and increasing the abundance of butyrate-producing gram-positive bacteria in mice in an IL-22–dependent manner." (PMID 34966278, 2021). "Neutralization of IL-22 blocked the protective effect of I3C on colitis and prevents I3C from dysbiosis and butyrate-induced remission." (PMID 34966278, 2021). "It has been postulated that the altered microbiota of Card9−/− mice were less capable of producing IAA and other AhR ligand necessary for the IL-22 production contributing to the hypersusceptibility to colitis." (PMID 34362137, 2021). "A dominant Th2 response causes lower IL-22 levels, consistent with our finding: PS23 FM upregulated the level of IL10 in the DSS-induced colitis mouse model to create a more anti-inflammatory environment, which inhibited IL22 expression." (PMID 34681392, 2021). "In an anti-CD4 and anti-CD90 antibody-depleting mouse colitis model, IL-6 was found to contribute to the activation and production of IL-17A, IL-22 and IFN-γ in intestinal ILC3s, a finding confirmed in isolated lamina propria cells from IBD patients." (PMID 34299236, 2021). "The authors demonstrated their ability to ameliorate the ongoing colitis through the induction of IL-22 and the down-regulation of inflammatory cytokines by targeting immune cells in absence of adverse events." (PMID 34299118, 2021).
colitis (continued). "Experimental models found that IL-22 is produced in neutrophils during colitis and in fibroblasts during rheumatoid arthritis." (PMID 34805416, 2021). "On the one hand, IL-22-knock-out mice develop a higher tumor burden, which was related to a substantially increased inflammatory activity after colitis induction by dextrane sulfate sodium." (PMID 33912578, 2021). "Ahr activity has been shown to alleviate colitis by regulating the levels of Il-22 and Il-17, and therefore Ahr has been suggested to maintain intestinal homeostasis by regulating the activities of intraepithelial lymphocyte, Treg, and Th17 cells." (PMID 34070845, 2021). "A previous study has confirmed that the blocking IL-22 pathway prolongs recovery in the DSS-induced colitis model." (PMID 34199820, 2021). "IL-22-deficient mice have increased susceptibility to acute dextran sulfate sodium (DSS)- and T cell-mediated colitis." (PMID 34868019, 2021). "Local gene delivery of IL-22bp, for instance, hindered IL-22-mediated goblet cell proliferation in a mouse model of acute DSS colitis." (PMID 33869257, 2021). "Tnfrsf11fl/flRorc Cre mice exhibited hyperresponsive CCR6+ ILC3s and increased IL-17/IL-22 production, presenting less severe colitis upon C. rodentium infection." (PMID 34659248, 2021). "Indole alkaloids have been proved as essential protective agents in colitis by activating AhR and inducing subsequent IL-22-depedent regeneration of mucosal barrier integrity." (PMID 34354708, 2021). "After DSS-induced colitis in caspase recruitment domain-containing protein 9 (Card9) knockout mice dysbiosis was associated with reduced IAA levels, reduced IL-22 production, and higher susceptibility to inflammation." (PMID 33562721, 2021). "Consistently, IAA levels were reduced in Card9−/− mice and the transfer of Card9−/− intestinal microbiota to germ-free wild type mice was sufficient to impair IL-22 activation and to increase the sensitivity to colitis." (PMID 34362137, 2021). "CARD9 is a susceptibility gene for inflammatory bowel disease, and it has been shown that CARD9 promotes recovery from colitis through the production of IL-22." (PMID 34362137, 2021). "Specifically, IL-22 protected from colitis in infectious or chronic inflammatory models or induced ileitis in the Toxoplasma gondii model." (PMID 33912578, 2021). "Experiments in mouse colitis models have linked IL-23-responsive NCR− ILC3s to the development IBD through the production of IL-17A, IL-22, and IFN-γ." (PMID 34299236, 2021). "While IL-22 definitely has a protective role on gut epithelium, it also promotes colitis in a context-dependent manner, especially when immune components are involved." (PMID 34992594, 2021). "IL-22 is one of the cytokines that belongs to the IL-10 family and can protect the gastrointestinal tract in the colitis models." (PMID 34199820, 2021). "Interestingly, cohousing wildtype mice with IL-22–deficient mice increased the severity of DSS-induced colitis in these wildtype mice, suggesting that the colitis might be ‘transmissible’ as has been shown for TRUC mice (mice that are deficient for both T-bet and Rag2)." (PMID 34603258, 2021). "CARD9 is a susceptibility gene for IBD that modulates the immune response against microorganisms and promotes recovery from colitis by inducing IL-22 production." (PMID 33562721, 2021). "This outcome is associated with intestinal barrier function improvement as well as amelioration of colitis in mice through an IL‐22‐dependent mechanism." (PMID 32410383, 2020). "When colitis was induced, in all groups, the clear expression pattern of Muc2, Reg3b, and Reg3g was lost, but Clec7a, Clec4n, and Il22 mRNA expression was still increased in HSD- vs. CD-fed mice." (PMID 33339337, 2020). "We investigated the expression of IL22-responsive transcriptional networks and the ER stress response in colonic tissue from CD patients with active colitis." (PMID 31792136, 2020).
colitis (continued). "In the current studies, we used Il22-/- mice to study the role of surface lipopolysaccharide in the regulation of AIEC colonization and AIEC-associated colitis." (PMID 33027280, 2020). "In a murine model of colitis mediated carcinoma, deficit in IL-22 ensured the development of fewer tumors." (PMID 33042126, 2020). "Mice with ILC3s-specific DR3 deletion show defective IL-22 secretion by ILC3s and increased susceptibility to DSS-induced colitis." (PMID 33193381, 2020). "Systemic administration of Reg3b significantly improved DSS-colitis in Il23RΔIEC mice by recruiting IL-22 secreting neutrophils supporting a protective role for Reg3b in colitis." (PMID 32076420, 2020). "In vivo, neutralization of GM-CSF in Rag2−/− mice subjected to DSS-induced colitis reduced IL-22 and GM-CSF production by CD90.2hi SCA1+ ILC3s." (PMID 32640223, 2020). "Apple polyphenols ameliorated DSS colitis and dampened the expression of proinflammatory transcripts, such as IL-6, IL-17, IL-22, and TNF-α." (PMID 33299531, 2020). "IL-12 was also shown to trigger initiation of colitis while IL-23 drives the chronic disease phase and it is one of the most potent inducers of IL-22." (PMID 32082288, 2020). "Strikingly, in an IL22-dependent model of chronic colitis, targeting IL22 alleviated colonic epithelial ER stress and attenuated colitis." (PMID 31792136, 2020). "Foxp3+ Treg cells can attenuate IL-22+ ILC3s-mediated colitis in mice through inhibiting the secretion of IL-23 and IL-1β by Cx3cr1+macrophages." (PMID 33193381, 2020). "Taken together, our results suggested that HSD enhanced immune response to DSS colitis via increased microbiota translocation, neutrophil accumulation, and related Il22 overexpression in the colon." (PMID 33339337, 2020). "Previous studies have shown that the abundance of Tricibacter in the gastrointestinal tract of colitis mice (DSS induced mice and IL-22 deficient mice) is decreased." (PMID 32621086, 2020). "Taken together these data indicate that IL22 plays a functionally important role in chronic colitis in TRUC mice and that targeting IL22, or pathological ER stress in the epithelium, alleviates colitis." (PMID 31792136, 2020). "In contrast, IL-22 also bears anti-tumor effects since blocking of IL-22 in early tumor initiation stages during DSS colitis leads to a reduced tumor burden." (PMID 32100077, 2020). "This is consistent with the ameliorative properties of IL22 on local intestinal inflammation in mouse colitis models." (PMID 32170183, 2020). "They additionally support IL-22 production, which was markedly increased after I3C supplementation in our colitis experiments." (PMID 32366032, 2020). "Many studies have identified that IL-22 plays a critical role in the repair of the intestinal epithelium during DSS-induced colitis." (PMID 33584726, 2020). "To determine the role of Enterobacteriaceae that accumulate during antibiotic-induced dysbiosis in colitis, we isolated Enterobacteriaceae species from the intestine of antibiotic-treated Il22−/− mice." (PMID 33027280, 2020). "Our results showed that the expression of IL-17A target genes OCLN and IL-22 decreased in the colorectum of ArgmyeKO mice during colitis, which likely contributed to disruption of the intestinal barrier integrity thereby aggravating colitis." (PMID 32391010, 2020). "Neutralization of IL-22 results in a significant reduction in the weight loss and colitis scores caused by the anti-CD40 injection, while IL-22 administration has been shown to drive more severe mucosal damage." (PMID 32670290, 2020). "Inhibition of NTPDases, which hydrolyzes extracellular eATP into adenosine, can aggravate DSS-induced colitis in mice dependent on reduced frequency of IL-22-producing ILC3s." (PMID 33193381, 2020). "While the IL-17 and IL-22 protein level remained unchanged, induction of colitis by TNBS significantly enhanced the transcription level of Il22 which was inhibited by both strains." (PMID 32210304, 2020).
colitis (continued). "This study suggested that I3C activation of AhR attenuates colitis primarily through the induction of IL-22, which leads to dysbiosis that promotes the production of anti-inflammatory butyrate." (PMID 33105907, 2020). "A single intraperitoneal administration of 1 μg per mouse (50 μg/kg) lowered the mortality, enhanced the level of IL-22 in colonic samples, and ameliorated colitis induced by TNBS or DSS." (PMID 32784381, 2020). "Modified apple polysaccharide inhibits colitis by decreasing the level of IL-22 and by increasing the expression of IL-22BP." (PMID 32486445, 2020). "In comparison with TRUC mice, germ line genetic deletion (TRUC Il22−/−) or neutralisation (anti-IL22 mAb) significantly reduced ER stress and completely attenuated colitis." (PMID 31792136, 2020). "Ahr−/− mice with reduced ILC3-produced IL-22 are prone to spontaneous colitis accompanied with increased segmented filamentous bacteria and Th17 cells." (PMID 32670290, 2020). "Together, such conflicting reports on the role of IL-22 in different colitis models reflect the complex function of ILC3 in relation to gut inflammation." (PMID 32670290, 2020). "CARD9 knockout mice exhibited downregulation in IL-22 signalling, resulting in impaired recovery from colitis when compared to wild-type mice." (PMID 30850234, 2019). "Using mice with ILC3 specific DR3 deletion (DR3ΔILC3) they showed that exacerbation of DSS colitis was due to the downregulation of IL-22 production by ILC3s, whereas treatment with recombinant IL-22 rescued survival of DR3ΔILC3 mice." (PMID 30972074, 2019). "Since disruption of the intestinal barrier provides a characteristic of DSS-induced colitis, IL-22 was demonstrated to play a pivotal role in counteracting inflammatory processes in this disease model." (PMID 31206517, 2019). "In summary, our findings indicate that TREM-1 protects mice against acute DSS-induced colitis by promoting M1 macrophage polarization and IL-1β production, which contributes to IL-22 production by ILC3 that restores epithelial barrier integrity." (PMID 31189465, 2019). "Further studies are required to understand the IL17-dependent and independent function of IL-22 and/or Ahr signaling in the protective role of M-cells in colitis." (PMID 30737385, 2019). "TP5 increased the expression of IL-22 and normalized the composition of gut flora which contributed to its therapeutic effect on colitis." (PMID 31695782, 2019). "The critical role of IL-22 in the protective effect of TP5 on colitis was further confirmed by administering the anti-IL-22 antibody (αIL-22), which completely abolished the effect of TP5." (PMID 31695782, 2019). "AHR is down-regulated in intestinal tissue of patients with IBD; and AHR signaling via IL-22 inhibits inflammation and colitis in the gastrointestinal tract of mice." (PMID 31001262, 2019). "IL-22 improves intestinal barrier function by regulating the expression of epithelial tight junction proteins and Ahr protects against colitis by suppressing T-cell response." (PMID 30737385, 2019). "AhR also increases IL-22 production to protect against trinitrobenzene sulfonic acid-induced colitis." (PMID 31816903, 2019). "There are many precedents for the appearance of IL-22 producing neutrophils in mammals in disease states, as seen during intestinal inflammation/colitis, and with Leishmania infections." (PMID 31306696, 2019). "To verify the importance of IL-22 in preventing the pathogenesis of DSS-induced colitis, we injected recombinant IL-22 into the peritoneal cavities of TREM-1-deficient mice every other day, starting 1 day prior to DSS administration." (PMID 31189465, 2019). "GELNs mdo-miR7267-3p-mediated targeting of the LGG monooxygenase ycnE leads to increased indole-3-carboxaldehyde, inducing the production of IL-22 and thus ameliorating mouse colitis via IL-22-dependent mechanisms." (PMID 31689969, 2019).